IRF1 (interferon regulatory factor 1)
Diseases named in the same sentence as IRF1 in open-access papers (continued):
Sharing a sentence is not in itself a finding about the gene and the disease.
Alzheimer disease (3 papers, 2021 to 2025). A progressive, neurodegenerative disease characterized by loss of function and death of nerve cells in several areas of the brain leading to loss of cognitive function such as memory and language. "BLNK assists in activation of immune cells, APOE codes for apolipoprotein associated with Alzheimer’s disease and IRF1 is activated by interferon gamma and regulates expression of antiviral genes." (PMID 34681730, 2021). "In the present study, we demonstrate that Interferon Regulatory Factor-1 (IRF-1), which is deficient in the brain of individuals with Alzheimer’s disease (AD), negatively regulates the O-GlcNAcylation levels of GluN1 through transcriptional regulation of the human OGA gene." (PMID 41029886, 2025). "Our results indicate that IRF1 can improve the cognitive function of 3xTg-AD mice by regulating the O-GlcNAcylation of GluN1, offering evidence that IRF-1 could serve as a novel therapeutic target for treating synaptic dysfunction in Alzheimer’s diseases." (PMID 41029886, 2025).
B cell lymphoma (3 papers, 2012 to 2025). "Moreover, to validate whether the BAP1/IRF1/CIITA axis is a major regulator of MHC-II genes’ expression in B cell lymphoma, we restored IRF1 in BAP1-KO A20 cell followed by RNA-Seq analysis and FACS analysis." (PMID 39817454, 2025). "IRF1 has been noted among the potential drivers of common B cell lymphoid neoplasms and interacts with multiple myeloma oncogene-1 protein (MUM1), which has a role in the progression of B cell lymphoma." (PMID 36306362, 2022).
Behcet disease (3 papers, 2009 to 2023). A chronic, relapsing, multisystemic vasculitis characterized by mucocutaneous lesions, as well as articular, vascular, ocular and central nervous system manifestations. "Polymorphisms in the IRF1 gene have been associated with Behçet disease, which often presents with uveitis." (PMID 36834715, 2023). "Lee and coworkers found the association of IRF1 polymorphism with Behcet’s disease in Koreans." (PMID 19816589, 2009).
brucellosis (3 papers, 2021 to 2025). Brucellosis is a bacterial infection that spreads from animals to people via unpasteurized dairy products or by exposure to contaminated animal products or infected animals. "Consistently, these genes associated with ‘interferon‐gamma response’ (e.g., IFNG, IRF1, SOCS1) are also enriched in brucellosis patients." (PMID 39135683, 2024). "However, chronic brucellosis localization in the mouse tail vertebrae was achieved when sublethal amounts of Brucella were used to infect IRF-1−/− mice which may be helpful in establishing a brucellosis-type osteoarthritis model." (PMID 39967734, 2025). "In brucellosis patients, the expression levels of many typical IFN‐γ/IFN‐I response genes, including IFITM3, B2M, GBP1, IRF1, IFI30, IFNGR2, and so forth, were higher than those in controls." (PMID 39135683, 2024). "In line with this, the enrichment of genes linked to the ‘interferon‐gamma response’ pathway (e.g., STAT1, IFNG, IRF1, B2M, GAPDH) was also consistently observed in brucellosis patients." (PMID 39135683, 2024).
cerebral malaria (3 papers, 2009 to 2024). A sequestration of Plasmodium falciparum in the brain, which can cause coma and/or seizures. "Although they did not examine the regulatory relationship or leukocyte binding, there is evidence of IRF1 promoting ICAM-1-mediated leukocyte-endothelial cell interactions in other experimental systems, for example, cerebral malaria in Irf1 gene-deficient mice." (PMID 36834715, 2023).
enterovirus infection (3 papers, 2020 to 2022). "In conclusion, the present study reveals a distinct mechanism by which the host elicits immune responses against enterovirus infections in the intestine through activating the TLR3/IRF1/type III IFN signaling pathway." (PMID 33203755, 2020). "Altogether, these results revealed a distinct mechanism by which the host elicited immune responses against enterovirus infections in intestine through activating the TLR3/IRF1/type III IFN axis." (PMID 33203755, 2020). "Taken together, these results revealed a mechanism by which host intestine elicits immune responses against enterovirus infections through activating the TLR3/IRF1/type III IFN signaling pathway." (PMID 33203755, 2020). "Although STING-dependent signaling is suppressed in the most cancerous intestine cells, we reported that similar to the normal FHC cells, cancerous HT29 cells showed active innate immune response in TLR3/IRF1/IFN signaling upon enterovirus infection." (PMID 33203755, 2020). "Mechanistic studies demonstrated that IFN-λ production is induced upon enterovirus infection through the Toll-like receptor 3/interferon regulatory factor 1 (TLR3/IRF1) signaling pathway in IECs." (PMID 33203755, 2020). "Furthermore, a recent report demonstrated a role for IRF-1 in the upregulation of type III IFNs in human IECs in response to enterovirus infection, confirming the relevance of this transcription factor in the cells that support RV replication." (PMID 33807175, 2021).
liver fibrosis (3 papers, 2018 to 2025). "The preferential binding of IRF1 to the A allele compared to the C allele would downregulate MERTK in patients carrying the A allele, protecting against liver fibrosis and hepatocarcinoma." (PMID 30477195, 2018).
lupus nephritis (3 papers, 2018 to 2024). Glomerulonephritis in the context of systemic lupus erythematosus. "For example, increased expression of miR-23 in serum is associated with renal damage in early lupus nephritis, whereas overexpression of miR-23 exhibits an ameliorating effect on lupus nephritis via suppressing IRF1 in vivo." (PMID 38027040, 2023). "MiR-130b and miR-302d are downregulated in kidney tissues from lupus nephritis or in monocytes from SLE and have as a target the interferon regulatory factor 1 and 9 respectively (IRF1; IRF9), which are involved in type I IFN response." (PMID 30322050, 2018).
male infertility (3 papers, 2011 to 2017). The inability of the male to effect fertilization of an ovum after a specified period of unprotected intercourse. "In the later stages of spermatogenesis, a decreased expression of the testicular miR-383 could inhibit the tumour suppressor, an interferon regulatory factor-1 (IRF1), which may provoke the male infertility and testicular germ cell tumour." (PMID 28881852, 2017).
metastatic tumors (3 papers, 2018 to 2024). "IRF-1 expression was dramatically increased in the CCl4-induced inflammation group, and IRF-1-positive structures were located mainly in the areas where metastatic tumors existing." (PMID 29695839, 2018). "TempO-Seq analysis showed upregulation of innate immune response and IRF pathway genes (IRF1, IRF7, IFNAR2, JAK1, STAT1), yet no reduction was observed in the metastatic tumors." (PMID 38516270, 2024).
nephritis (3 papers, 2016 to 2024). Inflammation of renal tissue. "MRL/lpr.IRF1-KO mice showed decreased inflammatory mediator production, decreased nephritis, and increased survival compared to MRL/lpr.IRF1-sufficient mice." (PMID 38256157, 2024). "IRF1 was identified as a direct target of microRNA (miR)-130b in mesangial cells in the kidney, and inhibiting IRF1 through miR-130b overexpression in NZB/W F1 lupus mice reduced IFN-accelerated nephritis progression, demonstrated by decreased proteinuria and glomerular lesions." (PMID 38256157, 2024).
serous ovarian carcinoma (3 papers, 2010 to 2020). "In this respect, one of the interesting genes identified as differentially expressed between high CD8+ TIL and low CD8+ TIL tumours and associated with DSS of late-stage serous ovarian cancer patients is interferon regulatory factor 1 (IRF-1)." (PMID 20664601, 2010). "Moreover, higher IRF1 expression is associated with better progression-free and overall survival in patients with high-grade serous ovarian carcinoma." (PMID 32326356, 2020).
Stroke (3 papers, 2012 to 2024). Sudden impairment of blood flow to a part of the brain due to occlusion or rupture of an artery to the brain. "Young rats also had better synchronized gene expression as was illustrated by the coordinated co-expression of genotoxic stress-induced genes Brca1 and Irf1 at day 3 post-stroke." (PMID 23251410, 2012).
acute lung injury (2 papers, 2021 to 2025). A condition of lung damage that is characterized by bilateral pulmonary infiltrates (pulmonary edema) rich in neutrophils, and in the absence of clinical heart failure. "Coincidentally, another study also indicated that interferon regulatory factor-1 (IRF-1) plays an important role in mediating alveolar macrophage pyroptosis during acute lung injury." (PMID 33613295, 2021).
anaemia (2 papers, 2009 to 2023). "Indeed, IFN-γ drives anemia by inhibiting the differentiation of early erythroid progenitors through the IRF-1/PU.1 axis." (PMID 37074208, 2023).
cognitive decline (2 papers, 2022 to 2025). "Other studies have suggested that angiotensin II type 2 (AT2) receptors can enhance spatial memory, and IRF-1 induces the expression of AT2 receptors, implying that IRF-1 exerts beneficial effects on cognitive decline through AT2 receptor signaling." (PMID 41029886, 2025). "The protective effect of IRF-1 on cognitive decline is evident under normal conditions; however, no significant impact on cognition was observed following treatment with chronic cerebral hypoperfusion." (PMID 41029886, 2025). "IRF-1 resists cognitive decline under normal conditions, but no obvious effect on cognition was observed in a bilateral common carotid artery stenosis mouse model." (PMID 35936778, 2022).
Cognitive impairment (2 papers, 2021 to 2022). Abnormal cognition is characterized by deficits in thinking, reasoning, or remembering. "Additionally, the deletion of IRF-1 in mice lead to elevated levels of cognitive impairment, supporting a role for IRF1 in cognitive function." (PMID 36437953, 2022). "Moreover, the deletion of interferon regulatory factor 1 (IRF1) resulted in cognitive impairment in mice." (PMID 34720873, 2021).
colorectal tumors (2 papers, 2021 to 2023). "There are few studies in PANoptosis and tumors, but a study have reported that IRF1-dependent PANoptosis activation can prevent colorectal tumors in mouse, suggesting that PANoptosis plays a broader role in cancer." (PMID 34869390, 2021).
dysplasia (2 papers, 2021 to 2023). A usually neoplastic transformation of the cell, associated with altered architectural tissue patterns. "Furthermore, the expressions of CD8 as a CTL marker (P = 0.001), γH2AX as a DSB marker (P = 0.031), IRF-1 as a transcriptional factor for PD-L1 (P = 0.005), and PD-L1 (P = 0.003) in UC-associated dysplasia/colitic cancer were significantly higher than that noted for SCRC." (PMID 34158547, 2021). "In the present study, dysplasia/CC had a higher positivity for the DNA damage marker γH2AX and IRF-1 regarding HLA-I expression than SCRC." (PMID 37686454, 2023). "We compared PD-L1 expression between patients with SCRC and UC-associated dysplasia/colitic cancer and determined the association between PD-L1 and the CD8+ T-cell/DSB/IRF-1 axis in UC-associated dysplasia/colitic cancer." (PMID 34158547, 2021). "However, the association of PD-L1/DSB/IRF-1 with sporadic colorectal cancer (SCRC), and UC-associated dysplasia/colitic cancer, remains elusive." (PMID 34158547, 2021).
embryonic carcinoma (2 papers, 2020 to 2022). "Its expression is high in embryonic carcinoma, binds to interferon regulatory factor -1 (IRF1), leading to its downregulation simultaneously with CDK2 and p21." (PMID 35465311, 2022).
eosinophilia (2 papers, 2017 to 2023). "The pro-allergic function of Irf1−/− Th9 cells was ameliorated by treatment with IL-9-neutralizing antibodies as determined by decrease in eosinophilia, in the numbers of mucus-producing cells and in inflammation." (PMID 28497800, 2017). "This group includes patients with classified conditions associated with secondary eosinophilia, including EGPA (however, eosinophilia in EGPA is not entirely secondary, as it has a partially genetic background related to the IRF1/IL5 gene variant)." (PMID 37215720, 2023).
Fanconi anemia (2 papers, 2013 to 2025). Fanconi anemia (FA) is a hereditary DNA repair disorder characterized by progressive pancytopenia with bone marrow failure, variable congenital malformations and predisposition to develop hematological or solid tumors. "A ChIP-chip study determined that IRF1 potentially regulates the Fanconi anemia pathway via its regulation of BRIP1 protein expression." (PMID 25893139, 2013). "A previous IRF1 ChIP-chip study identified a number of DNA damage gene targets and this data suggests that IRF1 may regulate other proteins involved in DNA damage signaling in addition to the Fanconi anemia gene, BRIP1." (PMID 25893139, 2013).
fibrosarcoma (2 papers, 2019 to 2022). A malignant mesenchymal fibroblastic neoplasm affecting the soft tissue and bone. "In fibrosarcoma cells, IRF3 and IRF7 mRNAs were detected, while IRF1 and MyD88 mRNAs were regulated." (PMID 35737804, 2022). "In a human fibrosarcoma cell line, IRF 1 (irf1) has been found to be induced substantially only by type II IFN,and a strong modulation of this transcript is now considered as a hallmark of Stat1 dimer signaling/GAS-specific ISG." (PMID 31142600, 2019).
gout (2 papers, 2018 to 2025). A condition characterized by painful swelling of the joints, which is caused by deposition of urate crystals. "For example, for the motifs IRF1 and IRF4, these are involved in the regulation of immune response and may influence inflammatory pathways, which are known to be associated with urate metabolism and gout." (PMID 40745483, 2025).
HCMV infection (2 papers, 2019). "Induction of the IFN-independent ISG viperin during HCMV infection is known to be induced by either IRF3 or IRF1, binding directly to its promoter, and this may also be the mechanism of IFIT1, IFIT2, IFIT3, CXCL10, Mx1, Mx2 and ISG15 upregulation." (PMID 30871003, 2019).
hepatitis C (2 papers, 2011 to 2024). "We also anticipate target TFs and miRNAs of hub genes so as to find out important regulatory factors at transcriptional level in MASH and hepatitis C. IRF1 is the most prominent TFs." (PMID 39605886, 2024). "qPCR analysis of liver biopsyspecimens demonstrated that these unannotated transcripts, as well as IRF1,TRIM22 and MET, were also upregulated in hepatitis C with mild inflammation andno fibrosis." (PMID 21359205, 2011). "The qPCRanalysis of biopsies showing mild hepatitis C without fibrosis provide evidence thatthe upregulation of IRF1, TRIM22, andMET are authentically due to HCV infection, and not due tomajor changes in liver tissue cell type." (PMID 21359205, 2011).
Hyperoxaluria (2 papers, 2023 to 2024). Increased excretion of oxalates in the urine. "The expression of IRF-1 is increased in the kidneys of mice with hyperoxaluria, and IRF-1 is considered to play a lithogenic role." (PMID 39633711, 2024). "In conclusion, our research gave the first evidence that ADSC-derived miR-23-enriched exosomes affected the polarization of M1 macrophages by directly inhibiting IRF1 and protecting against calcium oxalate stone formation in a hyperoxaluria rat model." (PMID 38027040, 2023).
hyperphosphatemia (2 papers, 2020 to 2021). Abnormally high level of phosphate in the blood. "In addition, a higher serum phosphate level along with dysregulated IRF1–PGC1α axis and energy metabolism remodeling were observed in adenine-induced CKD mice, further confirming the role of hyperphosphatemia in CKD-associated HF and involved mechanism." (PMID 32938919, 2020). "Our study suggests that control of hyperphosphatemia or targeted intervention on HP-mediated IRF1 elevation and PGC1α downregulation could be a potential therapy for reducing the risk of cardiovascular death in CKD patients." (PMID 32938919, 2020).
ischemia (2 papers, 2021). A hypoperfusion of the BLOOD through an organ or tissue caused by a PATHOLOGIC CONSTRICTION or obstruction of its BLOOD VESSELS, or an absence of BLOOD CIRCULATION. "The main finding is that 10 genes (Clec5a, CD14, Fgr, Hck, Anxa1, Lgals3, Irf1, Lbp, Ptx3, Serping1) may represent key molecular links underlying acute activation of immune cells in the hippocampus in response to experimental ischemia." (PMID 34944656, 2021). "Compared with that of the sham group, the expression of IRF‐1 was downregulated at following ischemia, whereas IRF‐1 protein expression showed a time‐dependent increased over the 2–24 h period after reperfusion." (PMID 34766137, 2021). "IRF‐1 can activate autophagy to aggravate hepatic ischemia–reperfusion via regulating JNK pathway." (PMID 34766137, 2021).
ischemic stroke (2 papers, 2021 to 2025). A stroke disorder caused by obstruction of blood flow to the brain, due to thrombotic (local blood clot formation) or embolic (due to a blood clot or other material traveling from another site) event. "IRF1 also induces pro-inflammatory responses in brain, and IRF1 inhibition reduces neurodegeneration and improves outcomes following ischemic stroke." (PMID 34504493, 2021).
kidney injury (2 papers, 2020). Trauma to the kidney. "Consistent with our current findings, AhR activation downregulates IRF1 and HIF-1α via miR-142a, which decreases M1 macrophage polarization, increases M2 macrophage polarization, and reduces pro-inflammatory cytokine levels to ultimately protect against CaOx nephrocalcinosis-mediated kidney injury." (PMID 33204326, 2020).
kidney stone (2 papers, 2021 to 2023). "M2-macrophages associated phagocytosis could suppress kidney stone development through serval mechanisms, including NLRP3, miR-93-TLR4/IRF1, and miR-185-5p/CSF1 pathways." (PMID 36932340, 2023).
lymph node metastasis (2 papers, 2020 to 2022). "Interferon regulatory factor 1 (IRF1) was associated with tumor stage, lymph node metastasis, and distant metastasis." (PMID 36727052, 2022).
lymphoproliferative disorders (2 papers, 2011 to 2012). "Another mouse model of lymphoproliferative disorder was established by persistent expression of HCV structural proteins through disruption of interferon regulatory factor-1 (irf-1 −/−/CN2 mice)." (PMID 22844326, 2012). "Another mouse model of lymphoproliferative disorder was established by persistent expression of HCV structural proteins through disruption of interferon regulatory factor-1 (irf-1_/_/CN2 mice)." (PMID 22084693, 2011). "Persistent HCV protein expression is established by targeted disruption of interferon regulatory factor-1 (irf-1), and high incidences of lymphoproliferative disorders are noted in irf-1−/− CN2 mice." (PMID 22084693, 2011). "The disruption of irf-1 enhances lymphoproliferative disorders." (PMID 22084693, 2011). "Irf-1 −/−/CN2 mice showed extremely high incidences of lymphomas and lymphoproliferative disorders." (PMID 22844326, 2012).
Mendelian susceptibility to mycobacterial diseases (2 papers, 2023). "IRF1 autosomal recessive (AR) loss of function (LOF) variants have been identified in two related patients presenting with Mendelian susceptibility to mycobacterial diseases (MSMD)." (PMID 37809068, 2023).